CXCR4 (C-X-C motif chemokine receptor 4)
Diseases named in the same sentence as CXCR4 in open-access papers (continued):
Sharing a sentence is not in itself a finding about the gene and the disease.
ovarian carcinoma (continued). "In a vitro experiment, the researchers established that tetrahydroxycurcumin prevents the spread and invasion of human ovarian cancer cells SKOV3 by regulating the expression of CXCR4 and CXCL‐12." (PMID 41179371, 2025). "CXCL12, also known as SDF-1 (stromal-derived factor 1), is a potent chemoattractant whose receptor CXCR4 is overexpressed on the surface of ovarian cancer cells." (PMID 40362280, 2025). "The utilization of LPAR and CXCR4 in ovarian cancer showcases a favorable approach in both diagnosis and targeted therapy." (PMID 40836974, 2024). "Herein, R54 reduced Foxp3 and DNMT1 transcription, as previously reported in murine ovarian cancer, where the CXCR4 inhibitor, AMD3100, selectively reduced intratumoral Foxp3 Tregs and DNMT1 determining loss of Tregs suppressive function in vitro and in vivo." (PMID 38704478, 2024). "CXCL12 was unable to induce EMT in IGROV1 CXCR4-KO, confirming the specific role of CXCR4 to promote CXCL12 mediated EMT in ovarian cancer and the ability of R54 in hinder this process." (PMID 39700131, 2024). "Due to the overexpression of CXCR4 in ovarian cancer, AMD-NP-PTX can be effectively delivered to the cancer site, inhibiting the CXCL12-CXCR4 axis and exerting chemotherapeutic activity with reduced off-target toxicity." (PMID 39114657, 2024). "CXCR4 expression is significantly upregulated in ovarian tumor cells, with a notably greater level observed in ovarian cancer and borderline tumors than in benign tumors." (PMID 39281319, 2024). "CAFs-secreted CXCL12 induced EMT and cisplatin resistance in epithelial ovarian cancer though CXCR4/Wnt/β-catenin pathway." (PMID 39759028, 2024). "CXCR4/WNT/BETA-CATENIN induction in ovarian cancer cells leads to cisplatin resistance and in vivo CXCR4 targeting inhibited intraperitoneal dissemination." (PMID 39700131, 2024). "Targeting CXCR4 with the new antagonist R54 consistently reverted the mesenchymal transition in human ovarian cancer cells reducing migratory and chemoresistance features." (PMID 39700131, 2024). "Aim of the work was to evaluate the effect of the newly developed CXCR4 antagonist R54 on human ovarian cancer cells aggressiveness." (PMID 39700131, 2024). "CXCL14 was exclusively identified in fibroblasts, whereas its corresponding receptor, CXCR4, was found in fibroblasts, ovarian cancer cells, and plasma cells." (PMID 39135097, 2024). "The new peptide CXCR4 inhibitor, R54 impaired CXCR4 activity reducing cell growth, migration and signalling in human ovarian cancer cells." (PMID 39700131, 2024). "Cisplatin has been found to inhibit the SDF1/CXCR4 axis and its impact on ovarian cancer metastasis; these findings are consistent with our research findings." (PMID 36986504, 2023). "Studies showed that CXCR4 is involved in resistance to chemotherapies, including paclitaxel, a taxane similar to docetaxel, in ovarian cancer and ER+ or triple-negative breast cancer cell lines." (PMID 37280713, 2023). "CXCL12 is present in 95% of ovarian cancer ascites, while CXCR4 is the only chemokine receptor expressed in ovarian cancer cells." (PMID 35406620, 2022). "The relative expression of SDF-1 and CXCR4 was positively correlated with epithelial ovarian cancer stages (P<0.00)." (PMID 35545781, 2022). "Previous studies confirmed that EGFR can enhance the expression of CXCR4 in some cancers, including breast and ovarian cancers." (PMID 35729596, 2022). "Based on the analysis results, we assumed that the expression of SDF-1 and CXCR4 in epithelial ovarian cancer patients was positively correlated with the staging of epithelial ovarian cancer." (PMID 35545781, 2022). "In order to evaluate CXCR4 expression in an additional hepatic metastatic mouse model, we used human ovarian cancer, distinct from UM, and verified this with MRI using ProCA32.CXCR4." (PMID 35145271, 2022).
ovarian carcinoma (continued). "We have demonstrated the early detection of stage 2 metastases using three different metastatic UM models and an ovarian cancer model with administration of ProCA32.CXCR4." (PMID 35145271, 2022). "Since CXCR4 expression has been identified as an independent prognostic factor for ovarian cancer patients, and inhibitors of CXCR4 improved overall survival of mice with metastatic ovarian cancer." (PMID 35145271, 2022). "We have achieved early detection of liver metastases originating from parental UM cells with differential expression of CXCR4, as well as primary ovarian cancer, with our CXCR4 targeted MRI contrast agent using metastatic murine models." (PMID 35145271, 2022). "This group also demonstrated that knockdown of CXCR4 reduces proliferation and invasion of ovarian cancer cells through modulating the Wnt/β-catenin pathway." (PMID 35397601, 2022). "It has been found that the introduction of oncolytic viruses equipped with CXCR4 antagonists can restore pathological signaling, diminish metastasis and decrease regulatory T cell enrichment in ovarian cancer." (PMID 35388021, 2022). "Spearman correlation analysis between the relative expression of CXCR4, and different epithelial ovarian cancer stages showed that the relative expression of CXCR4 was positively correlated with epithelial ovarian cancer stages (P<0.001)." (PMID 35545781, 2022). "Together, SDF-1 and CXCR4 were positively correlated in epithelial ovarian cancer staging (P<0.001)." (PMID 35545781, 2022). "Adding bevacizumab diminished the expression of related cancer markers SDF-1 and CXCR4 more than chemotherapy alone in patients with epithelial ovarian cancer." (PMID 35545781, 2022). "Silencing CXCR4 in human ovarian cancer cells reduces cell proliferation, migration and invasion and significantly decreases in vivo tumor development." (PMID 35406620, 2022). "At the same time, stable ovarian cancer cells with stem-like characteristics were altered after CXCR4 overexpression or knockdown." (PMID 35681259, 2022). "To evaluate the effects of CXCR4 expression on tumorigenesis in EOC, we examined CXCR4 expression in an epithelial cell line derived from the human ovarian surface and eight ovarian cancer cell lines." (PMID 35681259, 2022). "In this study, SDF-1 and CXCR4 had certain predictive value for the diagnosis and prognosis of recurrent epithelial ovarian cancer." (PMID 35545781, 2022). "Another chemokine receptor, CXCR4, is overexpressed in human ovarian cancer and its ligand CXCL12 has been shown to be present in ascitic fluid collected from patients with ovarian carcinoma." (PMID 35625966, 2022). "In particular, metapristone affected ovarian cancer metastasis through interrupting CXCL12/CXCR4 axis." (PMID 33413440, 2021). "An analysis based on clinical samples showed that ovarian cancer patients with high expression of CXCR4 were significantly less sensitive to chemotherapy and had a poor prognosis, suggesting that CXCR4 is the key molecules for chemotherapy resistance." (PMID 34759953, 2021). "It has also been reported that the inhibition of the CXCL12/CXCR4 pathways improves survival in ovarian cancer cells by preventing immunosuppression." (PMID 34307366, 2021). "The CXCL12/CXCR4 pathway enhances metastasis, invasion, migration, and the proliferation of ovarian cancer." (PMID 34307366, 2021). "CXCL12/CXCR4 promotes invasion of ovarian cancer cells by suppressing ARHGAP10 expression via the VEGF/VEGFR2 signaling pathway." (PMID 34907282, 2021). "The results showed that CXCRs were expressed in both cell membrane and cytoplasm of ovarian cancer tissues, among which CXCR4 expressions were the highest, and CXCR3, CXCR5, CXCR6, and CXCR7 were expressed in different degrees." (PMID 33829065, 2021).
ovarian carcinoma (continued). "Tregs overexpress CXCR4 in advanced cervical cancer, malignant pleural mesothelioma, ovarian cancer and renal cell carcinoma." (PMID 33937018, 2021). "The expression of CXCR3/4/7 mRNA in ovarian cancer tissues was higher than that in normal ovarian tissues, and the expression of CXCR4 was the highest (fold change = 306.413, P < 0.05)." (PMID 33829065, 2021). "Classes of OV currently being examined in ovarian cancer are Maraba virus armed with tumor antigen, Vaccinia virus armed with CXCR4 inhibitor, and adeno virus with granulocyte–macrophage colony-stimulating factor (GM-CSF)." (PMID 33407605, 2021). "This concept is supported by a previous investigation showing that targeting CXCR4 reduces peritoneal metastases of ovarian carcinoma cells." (PMID 34115261, 2021). "The CXCL12 peptide dimer was shown to inhibit migration, and upon increasing concentrations, induced cell death by mitotic catastrophe of CXCR4-expressing ovarian cancer cells." (PMID 34503058, 2021). "The combination of CXCR7 and CXCR4 is a very promising indicator for predicting the occurrence, progression, and prognosis of ovarian cancer." (PMID 33829065, 2021). "In ovarian cancer, a novel oncolytic vaccinia virus expressing a CXCR4 antagonist (OVV-CXCR4-A-Fc), in combination with DCs pulsed with tumor lysates, can modulate TME by reducing immunosuppressive elements with higher spontaneous antitumor immunity." (PMID 33937018, 2021). "CXCR4 overexpression is related to an aggressive phenotype and poor prognosis in ovarian cancer and is essential for cancer-initiating cell (CIC) maintenance, dissemination and metastatic spread to organs where CXCL12 is expressed." (PMID 33407605, 2021). "The notch pathway contributes to the migration and proliferation of ovarian cancer cells by the CXCR4/SDF1α chemokine system." (PMID 34307366, 2021). "CXCR4 is a critical determinant for tumor initiation, progression as well as metastasis of ovarian cancer." (PMID 33748162, 2021). "Another study focused on chemoresistant ovarian cancer reported a novel oncolytic vaccinia virus expressing a CXCR4 antagonist that can reduce the immunosuppressive network and increase tumor apoptosis and phagocytosis alone or in combination with doxorubicin." (PMID 33363463, 2020). "For example, in ovarian cancer cell lines, TNFα can behave as a signaling molecule within the producing cell or among the surrounding ones, and can induce CXCR4 expression through NF-κB, enhancing in this way cell invasion." (PMID 32391269, 2020). "We further verified the expression of TACC3 and CXCR4 protein in ovarian cancer tissues and normal tissues stained by immunohistochemistry with HPA." (PMID 33123295, 2020). "From them, CK19, MUC1, CD24, CD44, TIMP1, and CXCR4 appeared, characterizing the ovarian cancer circulating population." (PMID 32423054, 2020). "Only high expression of UBE2C, TK1, TACC3 and CXCR4 and low expression of MAOB were proved to be associated with poor prognosis of patients with ovarian cancer, suggesting the five genes were considered to be the key genes in ovarian cancer." (PMID 33123295, 2020). "Consistently, it was reported that CXCL12/CXCR4 axis triggered PGE2-induced accumulation of MDSCs in ovarian cancer microenvironment." (PMID 30678736, 2019). "But the same treatment, down-regulates CXCR4 expression in ovarian cancer, suggesting complicated relationship between Notch signaling and the CXCR4 expression." (PMID 31382985, 2019). "In the previous study, we found metapristone significantly down-regulated CXCR4 expression in ovarian cancer, leading to inhibition of tumor progression and metastasis." (PMID 31151472, 2019). "Subsequent studies have provided evidence that CXCR4 expression on ovarian cancer cells is involved in the mechanism of peritoneal and hematogenous dissemination." (PMID 29389895, 2018). "It has been shown that CXCR4 is increased by 2–15 times in ovarian cancer cells compared to normal ovarian cells at the mRNA level." (PMID 29783989, 2018).
ovarian carcinoma (continued). "In fact, blocking or silencing of CXCR4 was found to significantly reduce RhoA and Rac-1/Cdc42 expression levels and decrease ovarian cancer cell migration." (PMID 30261690, 2018). "Another study suggested that PGE2 regulates CXCL12 levels in malignant ascites from ovarian cancer patients and CXCR4 expression on MDSC." (PMID 30319622, 2018). "In particular, introducing an oncolytic virus equipped with a CXCR4 antagonist restored the pathologic signaling in a murine model of ovarian cancer, reduced metastatic spread and diminished regulatory T cell recruitment." (PMID 30319622, 2018). "A novel strategy for the treatment of drug-resistant ovarian cancer combines chemotherapy to increase immunogenic cell death and virally delivered CXCR4 to reverse the immunosuppressive tumor microenvironment." (PMID 30622535, 2018). "Adding to this, metastatic fibroblasts are also the only cells expressing CXCL12, which along with CXCR4 play a pivotal role across many cancers, including ovarian cancer." (PMID 30383866, 2018). "TCDD was first shown to downregulate CXCL12 and CXCR4 expression in breast and ovarian cancer cells." (PMID 28261155, 2017). "Blockade of SDF-1/CXCR4 in ovarian cancer using an oncolytic vaccinia virus vector expressing a CXCR4 antagonist inhibited tumor growth by reduction of immunosuppression and targeting of tumor-initiating cells." (PMID 29212254, 2017). "SDF-1 stimulates the invasion of ovarian cancer cells into the peritoneal cavity in the CXCR4-dependent manner." (PMID 28938623, 2017). "The expression level of CXCR4 is elevated by binding of ovarian cancer cells to ECM via β1 integrin." (PMID 28275576, 2017). "In a mouse model of ovarian cancer the CXCR4 antagonist, AMD3100, determined several anti-tumor effects including increased tumor cell death, reduced dissemination and better survival of the treated animals." (PMID 29100374, 2017). "Overexpression of CXCR4 has become an independent prognostic factor of poor survival in human epithelial ovarian cancer." (PMID 28938623, 2017). "For example, patients with high expression of C-X-C chemokine receptor 4 (CXCR4) have a poor prognosis among Asian women with ovarian cancer." (PMID 28415663, 2017). "One of these is CXCR4, thus confirming the prosed role of the CXCL12–CXCR4 axis in the progression of many tumor types, including ovarian cancer." (PMID 27215396, 2016). "Expression of another chemokine, chemokine (C-X-C) motif receptor 4 (CXCR4), is expressed on both mesothelial and cancer cells and correlates to worse survival rates in ovarian cancer patients." (PMID 27074785, 2016). "We aimed to isolate cells with stem cell features sorting the cells expressing CXCR4+CD133+ within ovarian cancer cell lines." (PMID 26020117, 2015). "With the intent to isolate CSC ovarian cancer, 37 primary tumor samples were evaluated for the expression of CXCR4/CD133 and CD44/CD24." (PMID 26020117, 2015). "SDF-1α and its specific receptor CXCR4 are highly expressed in a variety of tumors, including gastric, colorectal, breast, and ovarian cancers." (PMID 25609203, 2015). "Taken together these data demonstrate that CD133+CXCR4+ ovarian cancer cells display features of higher malignancy similar to what has been described for the cancer stem cell population." (PMID 26020117, 2015). "The exposure to >10 μM genistein downregulated CXCR4, inhibiting chemotaxis and chemoinvasion of breast and ovarian cancer cells towards CXCL12." (PMID 26703550, 2015). "Another report showed that the growth and metastasis of ovarian cancer cells expressing CXCR4 under suboptimal culture conditions were stimulated by the ligand CXCL12." (PMID 26083776, 2015). "Recently, meta-analyses strongly supported the prognostic and clinicopathological relevance of CXCR4 in breast, esophageal, colorectal, gastric, and ovarian cancer, as well as in renal cell carcinomas and gliomas." (PMID 26091099, 2015).
ovarian carcinoma (continued). "In the present study, CXCR4 was expressed in the cell membrane and cytoplasm of the ovarian cancer cell lines, SKOV3 and CAOV3." (PMID 24765180, 2014). "In conclusion, our meta-analysis showed that high CXCR4 expression was associated with poor prognosis in terms of OS and PFS in ovarian cancer." (PMID 24658065, 2014). "To assess CXCR4 expression in solid tumor cell lines, we performed flow cytometry analysis in HeyA8 ovarian cancer cells and showed weak cell surface CXCR4 expression (HeyA8)." (PMID 25514788, 2014). "The CXCR4 proteins expressed in the cell membrane and the cytoplasm of ovarian cancer cells, CAOV3 and SKOV3, were detected by immunocytochemistry." (PMID 24765180, 2014). "The aim of this study is to evaluate the prognostic significance of CXCR4 in ovarian cancer by performing a meta-analysis." (PMID 24658065, 2014). "Many studies indicated a close correlation exists between chemokine axis CXCL12/CXCR4 and ovarian cancer and recommend CXCR4 as an independent prognostic factor." (PMID 24658065, 2014). "In a previous study on ovarian cancer, out of 14 chemokine receptors only CXCR4 was expressed on the ovarian cancer surface, and CXCL12 was detected in the ascites of 63 patients." (PMID 24765180, 2014). "Chemokine stromal cell-derived factor-1 (SDF-1) and its receptors, CXCR4 and CXCR7, have been implicated in epithelial ovarian cancer progression and metastasis." (PMID 24765189, 2014). "More studies, especially larger scale and well-matched researches, are warranted to clarify the prognostic effect of CXCR4 on the outcome of ovarian cancer." (PMID 24658065, 2014). "We systematically searched for studies evaluating the relationship between CXCR4 expression and the outcome of ovarian cancer patients." (PMID 24658065, 2014). "More studies, especially large scale, multi-center and well-matched cohort research, were warranted to clarify the prognostic effect of CXCR4 on the outcome of ovarian cancer." (PMID 24658065, 2014). "With regard to the expression of the SDF-1 and CXCR4/CXCR7 axis in ovarian cancer, the majority of data originates from immunohistochemical studies." (PMID 24765189, 2014). "Limited data are available on the expression levels of SDF-1 and CXCR4 variants and CXCR7 in human epithelial ovarian cancer." (PMID 24765189, 2014). "The CXCL12/CXCR4 axis delivers surviving signals to hepatocellular carcinoma cells, ovarian carcinoma cells, and chronic leukemia cells, while CXCR4 blockade induces the apoptosis of these malignant cells." (PMID 24966464, 2014). "At the mRNA and protein levels, enhanced expression of SDF-1 and CXCR4 has been demonstrated in different malignancies, including epithelial ovarian cancer and ovarian cancer cell lines." (PMID 24765189, 2014). "The present meta-analysis aims to determine the value of CXCR4 as a prognostic marker for ovarian cancer." (PMID 24658065, 2014). "A study of the expression of 14 chemokine receptors showed that only CXCR4 was expressed within ovarian cancer cell lines." (PMID 24658065, 2014). "Recent reports have shown that C-X-C chemokine receptor 4 (CXCR4) is expressed in ovarian cancer and plays an important role in metastasis." (PMID 24658065, 2014). "The imaging reporter for CXCR4 activation in ovarian cancer complements our prior imaging system for directly quantifying CXCL12 binding to CXCR4." (PMID 23372646, 2013). "Our findings suggest that the increased expression of CD164 is involved in ovarian cancer progression via the SDF-1α/CXCR4 axis, which promotes tumorigenicity." (PMID 24094005, 2013). "Approximately 60% of patients with ovarian cancer have CXCR4 on malignant cells, and these patients have significantly reduced overall survival." (PMID 23372646, 2013). "Chemokine CXCL12 and receptor CXCR4 have emerged as promising therapeutic targets for ovarian cancer, a disease that continues to have a dismal prognosis." (PMID 23372646, 2013).